CBX7 (chromobox 7)
Diseases named in the same sentence as CBX7 in open-access papers (continued):
Sharing a sentence is not in itself a finding about the gene and the disease.
cancer (continued). "Therefore, it is reasonable to hypothesize that the loss of expression of CBX7 may play a key role in the cancer progression." (PMID 24865347, 2014). "In cell line models of PCa, for example, CBX7 disrupts normal cell cycle regulation by repressing the tumor suppressor genes p16INK4A and p14ARF, thereby accelerating cancer progression and contributing to uncontrolled cell growth." (PMID 40175347, 2025). "CBX7 is a multifaceted protein that plays critical roles in physiological processes and pathological conditions, particularly cancer." (PMID 40175347, 2025). "Via the AKT-NF-κB-miR-21 and p16 pathways, CBX7 exerts control over the stem cell-like properties of cancer cells." (PMID 38413558, 2024). "We obtained 74 dysregulated SRGs between normal and cancer tissues, among which six genes (RPS6KA6, ABI3, PTTG1, E2F1, CBX7, and SPOP) were associated with the OS of CC patients." (PMID 37768206, 2023). "Chromobox homologue 7 (CBX7) is a member of the polycomb group family that plays a pivotal role in regulating cellular processes in human cancers." (PMID 35646140, 2022). "Nevertheless, the mRNA expression of CBX7 was the highest in normal tissues, and as the cancer stage increased, the mRNA expression of CBX7 tended to decrease." (PMID 35464847, 2022). "In these malignancies, downregulation of CBX7 correlated with lower cancer aggressiveness and favorable prognosis, suggesting an oncosuppressor role of CBX7." (PMID 36292141, 2022). "In cancer, Cbx7 was shown to possess dualistic role, either promoting or suppressing cancer progression, depending on cancer type and molecular interactors." (PMID 36361869, 2022). "Among the 8 CBXs family members, the expression levels of CBX1/3 were significantly upregulated, whereas CBX7 expression was significantly downregulated in other cancer types." (PMID 35969177, 2022). "CBX7 decreased expression has been reported for many carcinomas, such as breast, lung, colorectal, and thyroid." (PMID 36292141, 2022). "Cancer cell invasiveness was significantly enhanced when CBX7 was knocked down in 5637 cells, but overexpression of CBX7 suppressed T24 and UMUC-3 cell invasiveness." (PMID 34035231, 2021). "CBX7 is one of the Polycomb group complexes, which can function independently in the initiation and progression of various cancers." (PMID 33748425, 2021). "One of the proposed mechanisms for cancer suppression is that CBX7 exerts a cancer suppressor effect by inhibiting the expression of cyclin E." (PMID 34659360, 2021). "CBX7 participates in various pathways and plays different physiological effects in different cancers." (PMID 34659360, 2021). "On the contrary, miR-18a shows a cancer suppressor effect in primary ovarian tumors, due to the dual role of CBX7 as a bridge molecule in different cancers progression." (PMID 34659360, 2021). "Consistently, AKR1B10 overexpression induced cancer cell aggressiveness, whereas suppression of AKR1B10 by siRNA or its small molecular inhibitor, oleanolic acid, reversed the CBX7 deficiency-induced cellular effects." (PMID 34035231, 2021). "For its anti-cancer effect, CBX7 participates in different pathways according to the different tissue environments." (PMID 34659360, 2021). "Limited by our understanding of various cancer pathways, we describe some of the regulatory pathways in which CBX7 participates in cancers." (PMID 34659360, 2021). "More importantly, in this review, we briefly illustrated the duality of the interaction between CBX7 and various RNAs in cancers." (PMID 34659360, 2021). "On the other hand, since miR-181 binds to the mRNA 3′-UTR of CBX7, the expression of CBX7 is restricted, thus forming a synergistic cycle that promotes cancers." (PMID 34659360, 2021). "In a similar way, the Chromobox protein homolog 7 (CBX7) was shown to induce methylation of gene promoters and suppress gene expression in adult cancer, confirming the implication of histone modifications and bivalent genes in tumorigenesis." (PMID 33430434, 2021).
cancer (continued). "In cancers, CBX7 plays a dual role; On the one hand, it contributes to cancer progression in some cancers by inhibiting oncosuppressor genes." (PMID 34659360, 2021). "Clinically, the expression of CBX7 in different cancers is inconsistent for cancer progression, showing double-sidedness." (PMID 34659360, 2021). "On the other hand, other investigators claimed that CBX7 serves as a tumor suppressor gene in certain types of cancers including breast cancer, pancreatic cancer, lung cancer, thyroid cancer, colon cancer, bladder cancer and brain cancer." (PMID 32415167, 2020). "The upregulation of the mRNA of CBX1/2/3/4/5/8 and downregulation of CBX7 were found to be significantly correlated to the nodal metastatic status and individual cancer stage in GC patients." (PMID 33344640, 2020). "In these cancers, CBX7 repressed senescence- and apoptosis-related genes such as Ink4a/Arf and Trail." (PMID 32415167, 2020). "Recently, a number of microRNAs (miRNAs) have been identified to regulate the expression of CBX7 in human cancers." (PMID 31709304, 2019). "Accumulated evidence has dissected the mechanism of CBX7 in regulation of cell growth in human cancer." (PMID 31709304, 2019). "Chromobox protein homolog 7 (CBX7), a member of the polycomb group (PcG) family of proteins, is involved in the regulation of cell proliferation and cancer progression." (PMID 29422082, 2018). "As a member of PcG family proteins, CBX7 can function independently in the initiation and progression of various cancer types." (PMID 29422082, 2018). "Cbx7 as a component of polycom repressive complex 1 has functions in cancer cell development and extension of cellular life span." (PMID 28053699, 2017). "Previous studies have found that CBX7 positively regulates DKK1 transcription via enhancing histone acetylation in breast the cancer cell line MCF7." (PMID 28388562, 2017). "Downregulation of both miR-155 and CBX7 was observed in most of the carcinoma samples in comparison with the normal colon mucosa." (PMID 28259135, 2017). "Consistently, two studies, in thyroid and pancreatic carcinomas, report a direct correlation between the CBX7 expression and the E-cadherin levels." (PMID 28259135, 2017). "CBX7 is capable of upregulating E-cadherin indicating that it plays a critical role in later stages of cancer progression." (PMID 27449098, 2016). "CBX7 contributes, in fact, to prevent cancer progression by positively regulating the expression of the E-cadherin through the interaction with the HDAC2 protein and the following inhibition of the HDAC2 activity." (PMID 25595895, 2015). "In order to further elucidate the effect of CBX7 on cancer cell migration, SW480 cells transiently transfected with the Cbx7 or control vector were injected into the tail vein of SCID mice, and the pulmonary metastases were subsequently analyzed." (PMID 25881303, 2015). "The Alu-normalized Cbx7 mRNA levels were significantly increased in SM tissues when compared with CC tissues or colon biopsies taken from non-cancer patients (Student’s t-test, P < 0.036 or 0.007)." (PMID 25881303, 2015). "It is likely that both the decreased number of CBX7-positive lymphoid cells in the CC tissues, and the increased number of lymphocytes infiltrating into stromal tissues around cancer cells contributes to the downregulation of Cbx7 expression in CCs." (PMID 25881303, 2015). "We have previously demonstrated that CBX7 is able to inhibit the expression of the SPP1 gene, encoding the chemokine osteopontin that is over-expressed in cancer and has a critical role in cancer progression." (PMID 25595895, 2015). "CBX7 is a Polycomb group protein that shows variable expression changes in various cancers that are often contradictive." (PMID 25881303, 2015). "The qRT-PCR assay offers significant advantages over the hemi-quantitative immunohistochemistry assays for detecting Cbx7 expression changes in cancers." (PMID 25881303, 2015).
cancer (continued). "CBX7 is able to negatively regulate cell proliferation in thyroid, colon and lung carcinoma cell lines in which the expression of CBX7 was restored while MEFs from Cbx7−/− mice showed a higher cell proliferation rate compared with wild type ones." (PMID 25595895, 2015). "More recently, miRNA-181a was established as a direct regulator of RING2 (PRC2) and CBX7 (PRC1) in cancer." (PMID 24217920, 2014). "Taken together, the data reported here indicate that CBX7 negatively or positively controls the expression of several genes coding for proteins having a critical role in human cancer progression." (PMID 24865347, 2014). "CBX7 is a tumor suppressor in multiple cancer types, such as lung cancer, pancreatic cancer, colon cancer and thyroid cancer, but serves as an oncogene in gastric cancer and lymphoma." (PMID 25360999, 2014). "We have previously shown that the expression of CBX7 is drastically decreased in several human carcinomas and that its expression progressively decreases with the appearance of a highly malignant phenotype." (PMID 24865347, 2014). "Particularly, CBX7 has an important role in cellular life span and is directly involved in the regulation of several genes frequently silenced in cancer." (PMID 23306151, 2013). "This is the first time to find that CBX7 regulates cellular migration in in vitro model, and provide preliminary direct evidence for the possibility of CBX7 regulating the metastasis of cancer." (PMID 20723236, 2010). "Among the CBX family members, CBX7 plays different roles in various types of cancer." (PMID 39988672, 2025). "CBX7 could differentially modulate the expression of crucial genes involved in cancer progression due to its ability to bind to chromatin and recruit PRCs." (PMID 37791390, 2024). "CBX7 is known to have a dual role in cancer cell proliferation." (PMID 38426219, 2024). "Further studies are needed to determine whether epigenetic functions mediated by Cbx3/HP1γ and Cbx7 are sufficient to promote cancer stemness." (PMID 36361869, 2022). "Here, we focused on studying the cancer related role of CBX7 in ccRCC." (PMID 35342353, 2022). "The downregulation of CBX7 is closely correlated with cancer aggressiveness and poor prognosis." (PMID 35646140, 2022). "Some works of literature have reported that CBX7 is carcinogenic in several types of cancer." (PMID 36246611, 2022). "As for CBX7, it is the most well-studied protein among CBXs in cancer." (PMID 36140750, 2022). "On the other hand, this is the first report of negative association between CBX7 upregulation and cancer stemness." (PMID 36361869, 2022). "We suggest that in contrast to normal stem cells, Cbx7 represses cancer stemness." (PMID 36361869, 2022). "Thus, the elevated levels of Cbx7 observed in decreased cancer metastasis are consistent with our findings that N/D/S neurons express higher levels of Cbx7 and migrate shorter distances." (PMID 36517477, 2022). "Subsequent studies showed that CBX7 inhibited cancer cell proliferation and invasion." (PMID 35342353, 2022). "In addition, a clear correlation between downregulation of CBX7 and poor prognosis has been found in many types of cancers." (PMID 35342353, 2022). "The function of Chromobox 7(CBX7) in cancer remains controversial." (PMID 35125116, 2022). "Paradoxical roles of CBX7 had been shown in different malignant carcinomas." (PMID 35464847, 2022). "MicroRNAs have obvious tissue specificity and can interact with CBX7 to affect cancer progression." (PMID 34659360, 2021). "Among the CBX family members, CBX7 shows opposite functions in different cancer types." (PMID 34035231, 2021). "The mRNA expression level of CBX7 in cancer tissues was lower than that in normal tissues." (PMID 34117289, 2021). "However, pathologically, abnormal expression of CBX7 can lead to an imbalance of gene expression, which is closely related to the occurrence and progression of cancers." (PMID 34659360, 2021).
cancer (continued). "It would be interesting to assess whether CBX7 can be used as an intermediate molecule between cancers and immunity." (PMID 34659360, 2021). "In conclusion, CBX7 expression is a key factor in the occurrence and progression of cancers." (PMID 34659360, 2021). "Some lncRNAs can directly or indirectly influence the role of CBX7 in cancer progression." (PMID 34659360, 2021). "Based on the circumstances regarding CBX7 in cancers, it may be bold to speculate that the double-sidedness of CBX7 in cancer progression is closely related to its regulatory pathways." (PMID 34659360, 2021). "Downregulation of CBX7 was shown to play a critical role in cancer progression." (PMID 34261540, 2021). "CBX7 expression is the most important characteristic of CBXs in cancer-related research." (PMID 34117289, 2021). "Recently, the contact between CBX7 and DNA damage repair has emerged in cancers." (PMID 34659360, 2021). "Many studies found that CBX7 expression is decreased in many cancer tissues." (PMID 34117289, 2021). "Similarly, other molecules that use CBX7 as an intermediate for physiological effects can also play a dual role in different cancer progression, such as miR-18a." (PMID 34659360, 2021). "Though dysregulation of CBX7 has been reported in multiple cancers, its specific role and clinical relevance in UBC remain unclear." (PMID 34035231, 2021). "CBX7 can play its duality in different cancer tissues, but it could be beneficial to the immune system of the human body." (PMID 34659360, 2021). "CBX6 and CBX7 have been found to play contradictory roles in human cancers." (PMID 34395271, 2021). "In addition, this study will help develop isoform-selective inhibitors of CBX7 for treating cancers." (PMID 32415167, 2020). "Moreover, the downregulation of CBX7 mRNA expression was markedly correlated with nodal metastatic status and individual cancer stage and poor OS and FP in GC patients." (PMID 33344640, 2020). "Further studies could help us understand which isoforms of CBX7 play major roles in different types of cancer." (PMID 32415167, 2020). "It is likely that the role of CBX7 in cancer is diverse, depending on the type of tissue." (PMID 31211140, 2019). "Moreover, downregulation of CBX7 is correlated with poor prognosis and aggressiveness in a variety of human cancers." (PMID 31709304, 2019). "Several studies have shown that CBX7 could regulate the expression of E-cadherin in a variety of human cancers." (PMID 31709304, 2019). "Conflicting roles of CBX7 had been found in different kinds of human cancers." (PMID 30481161, 2018). "Moreover, the restoration of CBX7 expression in carcinoma cells of different origin results into a reduced growth rate, blocking the cells in the G1 phase of the cell cycle." (PMID 28259135, 2017). "Moreover, we have also shown that CBX7 counteracts the HMGA-induced activation of the SPP1 gene, encoding the chemokine osteopontin, that is highly overexpressed in several human carcinomas and has a key function in malignant transformation." (PMID 28259135, 2017). "Hence, we reason that miR-375 exerts its oncogenic properties by targeting CBX7 and thus regulating important cancer pathways." (PMID 27449098, 2016). "However, analysis of many types of cancers revealed that the Cbx7 expression levels were significantly altered, but the changes were often considerably contradictive." (PMID 25881303, 2015). "The Transwell migration and Matrigel invasion assays were further used to study whether CBX7 directly affects metastasis of cancer cells transient transfected with the Cbx7 expression vector." (PMID 25881303, 2015). "Interestingly, although the average Cbx7 mRNA level in SMs was significantly higher than CCs, it was also significantly higher than in normal colon control tissues from non-cancer patients." (PMID 25881303, 2015). "It cannot be excluded that Cbx7 may be upregulated in SMs as a B-cell infiltration-related host response to the presence of cancer cells." (PMID 25881303, 2015).
cancer (continued). "Finally, we asked if the predicted regulators (UHRF1, WHSC1, and CBX7) influence DNAm at the same genomic loci across cancer types." (PMID 26169266, 2015). "Similarly, loci whose DNAm levels correlated most strongly with decreased gene expression of CBX7 were also most significantly highly ranked in the other cancer types." (PMID 26169266, 2015). "The Cbx7 expression levels in human cancers are highly variable and often contradictive." (PMID 25881303, 2015). "Our results support the hypothesis that the deregulation of the CBX7/HMGA1b axis might contribute to cancer progression through the modulation of the SPP1 gene expression." (PMID 25595895, 2015). "CBX8 could have different mechanisms in different cancer types, as CBX7 also plays diverse roles in different cancers." (PMID 25360999, 2014). "We found that CBX7 negatively or positively regulates the expression of several genes (such as SPP1, SPINK1, STEAP1, and FOS, FOSB, EGR1, respectively) associated to cancer progression, by interacting with their promoter regions and modulating their transcriptional activity." (PMID 24865347, 2014). "Indeed, these mice develop liver and lung adenomas and carcinomas, and accordingly, mouse embryonic fibroblasts (MEFs) derived from the cbx7 knockout mice have a higher growth rate and a reduced susceptibility to senescence than their wild type counterparts." (PMID 24865347, 2014). "Interestingly, in Normal tissues from 18 non-cancer patients, we found that transcription of Cbx7 was positively correlated with those of Ring1, Bmi1, Mel18, and Phc2, but not with those of Cbx8 and Ezh2 (Ps<0.01)." (PMID 21060834, 2010). "However, in GCN and GC samples from 20 cancer patients, such correlation was progressively disturbed, especially between Cbx7 and Ring1/Mel18." (PMID 21060834, 2010). "Regulation of INK4a/ARF locus by CBX7 also needs further confirmation in cancer cells." (PMID 20723236, 2010). "Others have reported downregulation of Cbx7 in human cancer tissues previously." (PMID 21060834, 2010). "Our results suggest that CBX7 regulates cell migration and that overexpression of CBX7 may contribute to cancer metastasis." (PMID 20723236, 2010). "Furthermore, considerable evidence has verified that CBX7 possesses an antitumor effect in cancers." (PMID 35646140, 2022). "But other studies have found that CBX7 may play an anticancer role in some cancers." (PMID 36246611, 2022). "Therefore, CBX7 could work with different partner molecules to produce different effects (pro-cancer or anti-cancer)." (PMID 34659360, 2021). "Therefore, further studies are still needed to fully evaluate the role of CBX7 in cancers." (PMID 34046352, 2021). "Therefore, actively guiding the expression of CBX7 in vivo according to cancer types may be helpful in guiding the clinical progress of cancer treatment." (PMID 34659360, 2021). "Furthermore, CBX7 is involved in cancer-related immune response and DNA repair." (PMID 34659360, 2021). "Besides, the cellular effects mediated by CBX7 are diverse in different cancer environments." (PMID 34659360, 2021). "Furthermore, CBX7 can also increase the sensitivity of cancer cells to chemical drugs." (PMID 34659360, 2021). "Moreover, the mRNA expression of CBX7 was found to be downregulated in all cancer stages." (PMID 33344640, 2020). "However, several studies have shown that CBX7 could be an oncogene in multiple types of human cancers." (PMID 31709304, 2019). "However, in some other cancers, lower expression of CBX7 was observed." (PMID 29422082, 2018). "However, the role of CBX7 in cancer development remains controversial." (PMID 29422082, 2018). "Hence, we speculate that the expression and effects of CBX7 are tissue and cell type specific, and future experiments are required to explore the diversity of CBX7 functions among various cancers and the molecular mechanisms involved." (PMID 28388562, 2017).